ATR (ATR checkpoint kinase)
Diseases named in the same sentence as ATR in open-access papers (continued):
Sharing a sentence is not in itself a finding about the gene and the disease.
metastatic cancer (2 papers, 2019 to 2020). A carcinoma which has spread from the original site of growth to another anatomic site. "In our study, users of ATr blockers had a smaller proportion of metastatic cancer cases, a lower likelihood of initiation of ADT therapy, and lower PCa mortality as compared to patients in the other groups." (PMID 32598349, 2020).
metastatic colorectal cancer (2 papers, 2023). "In addition, a recent study showed that a metastatic colorectal cancer patient with ATM loss of function mutation benefited from an ATR inhibitor M6620 (VX‐970) monotherapy." (PMID 36161776, 2023).
metastatic melanoma (2 papers, 2025). A melanoma that has spread from its primary site to another anatomic site. "Similarly, targeting ATR in ALT-associated HRD (homologous recombination defect) tumors has produced remarkable responses in metastatic melanoma." (PMID 41422096, 2025).
oesophageal cancer (2 papers, 2024). "The CHARIOT study demonstrated that the ATR inhibitor (Berzosertib) combined with chemoradiotherapy is feasible and well tolerated in oesophageal cancer patients." (PMID 38970106, 2024). "Berzosertib is a first in class, selective and potent inhibitor of ATR and several in vitro and in vivo preclinical studies have shown the radiation sensitising effects of ATR inhibition including synergy with berzosertib in oesophageal cancer models." (PMID 38129525, 2024). "Preclinical studies have shown that ATR is activated following cisplatin treatment and that ATR inhibition can profoundly sensitise tumour cells, including oesophageal cancer cells to platinum-based chemotherapy and radiotherapy." (PMID 38129525, 2024).
osteoporosis (2 papers, 2007 to 2022). A condition of reduced bone mass, with decreased cortical thickness and a decrease in the number and size of the trabeculae of cancellous bone (but normal chemical composition), resulting in increased fracture incidence. "However, the involvement of ATM/ATR and the relationship between RAD51 and ATM/ATR in osteoporosis remains unknown." (PMID 35176943, 2022). "However, the role of RAD51 and its interaction with ATM/ATR in osteoporosis remains unclear." (PMID 35176943, 2022).
pancreatic NET (2 papers, 2020 to 2024). "Hallmarks of NET G1/G2 are loss of chromosome 18, inactivation of CDKN1/APC, and gain of chromosomes 4, 5, and 14 in NET of the small intestine and inactivation of MEN1/chromosome 11, DAXX/ATR, and PTEN/TSC2 in pancreatic NET." (PMID 33228231, 2020).
parvovirus infection (2 papers, 2024 to 2025). "Interestingly, ATR- or ATM-dependent DNA damage responses are also induced by parvovirus infections and are important for viral DNA replication." (PMID 39541416, 2024). "Both autonomous (MVM, HBoV, H-1PV) and dependo- (AAV2) parvovirus infection can activate several repair mechanisms that are typically involved in resolving DNA breaks and maintaining genome stability, including ATM and ATR kinases." (PMID 40284937, 2025).
skin cancer (2 papers, 2020 to 2025). "Since ATR seems to exhibit dual roles in different skin cancers, it is imperative to delineate the exact interaction between PLK4 and ATR/CHEK1 pathways." (PMID 40940791, 2025). "Additionally that UV affects the ATR/CHEK1 pathway, it would be interesting to study UV-mediated dysregulation of PLK4/ATR/CHEK1 axis in skin cancer models." (PMID 40940791, 2025).
testicular cancer (2 papers, 2020 to 2021). A primary or metastatic malignant neoplasm that affects the testis. "Knocking down ASH2L in these cells and in the NT2D1 testicular cancer cell line rendered them resistant to bleomycin, etoposide, and cisplatin but did not affect their sensitivity toward ATM or ATR inhibitors." (PMID 33257682, 2020).
thyroid cancer (2 papers, 2016 to 2024). "Therefore inhibiting other key components of the DRR response such as ATR and DNA-PKcs may sensitise thyroid cancer cells to DNA damaging therapy." (PMID 27527858, 2016). "The effect of caffeine (inhibitor of ATM and ATR) and UCN-01 (CHK1 inhibitor) was evaluated in cell cycle progression of thyroid cancer cells after γ‐radiation or doxorubicin treatment." (PMID 38380364, 2024).
type 2 diabetes (2 papers, 2015 to 2025). "In addition, a feature of both WS and ATR-SS is the presence of inflammatory conditions such as type II diabetes, which is in contrast to NBS where inflammatory conditions are not found; activated p38 is strongly associated with inflammatory conditions." (PMID 25214013, 2015).
urothelial carcinoma (2 papers, 2023). A malignant neoplasm derived from the transitional epithelium of the urinary tract (urinary bladder, ureter, urethra, or renal pelvis). "Based on these concerns, future studies evaluating ATR inhibitors may focus on pre-selecting by ATM mutational status given its prevalence in urothelial carcinoma to identify those most likely to benefit from therapy." (PMID 36604210, 2023). "ATR inhibition is being studied in multiple types of cancer, including advanced urothelial carcinoma where there remains an unmet need for novel therapies to improve outcomes." (PMID 36604210, 2023). "Four ATR inhibitors are under active investigation in early-phase clinical trials in a variety of cancer types, including advanced urothelial carcinoma." (PMID 36604210, 2023). "While the application of ATR inhibitors in urothelial carcinoma is still in its early stages of research, a potential new therapeutic approach involves combining Wee1 and ATR inhibition with conventional platinum-based chemotherapy." (PMID 37296592, 2023).
ZIKV infection (2 papers, 2021 to 2022). "Defective ATR/Chk1 checkpoint has been reported previously in ZIKV infection in human NPC, while the ATM/Chk2 checkpoint was reported active, but only at 48 hpi." (PMID 35412344, 2022).
Acidosis (1 paper, 2021). Abnormal acid accumulation or depletion of base. "Acidosis had little effect on cyclin-dependent kinase (CDK) or casein kinase 2 activity, two members of the CMGC family, or Ataxia telangiectasia mutated (ATM)/ATM and RAD3-related (ATR) activity, but reduced the phosphorylation of MAPK/CDK substrates." (PMID 34113235, 2021).
AIDS (1 paper, 2023). A syndrome resulting from the acquired deficiency of cellular immunity caused by the human immunodeficiency virus (HIV). "There was a significant association between the ATR rs75069062 and Chk1 rs10893405 and the clinical stage of AIDS." (PMID 37468905, 2023). "Rs75069062 in ATR gene and rs10893405 in Chk1 gene were associated with AIDS progression among MSM population in northern Chinese." (PMID 37468905, 2023).
aneurysm (1 paper, 2020). Bulging or ballooning in an area of an artery secondary to arterial wall weakening.
anxiety disorder (1 paper, 2020). A category of psychiatric disorders which are characterized by anxious feelings or fear often accompanied by physical symptoms associated with anxiety. "In contrast to our hypothesis, FA in the ATR, but not in the UNC, was associated with difficulties in emotion regulation, which appear to not be specific to BD or the risk for BD as they were also associated with the diagnosis of anxiety disorders." (PMID 31883419, 2020).
aortic stenosis (1 paper, 2022). Aortic valve stenosis is a aortic valve disease caused by the incomplete opening of the aortic valve. "Our studies on cardiac biopsies from severe aortic stenosis with patients with HFpEF-like syndrome further supported these findings, highlighting the involvement of both ATR/CHK1 and ATM/CHK2 axis." (PMID 35811699, 2022).
asthma (1 paper, 2024). "In addition, several KEGG and Reactome pathways revealed that the distinction in risk subgroups may have relationships with Neuroactive ligand−receptor interaction, Asthma, Amplification of signal from the kinetochores as well as Activation of ATR in response to replication stress." (PMID 38240708, 2024).
ataxia-telangiectasia-like disorder (1 paper, 2022). An autosomal recessive condition caused by mutation(s) in the MRE11A gene, encoding double-strand break repair protein MRE11. "The effects of ATM/ATR are focused on ataxia-telangiectasia-like disorders and malignancies." (PMID 35176943, 2022).
autism spectrum disorder (1 paper, 2022). A spectrum of developmental disorders that includes autism, and Asperger syndrome.
bipolar disorder (1 paper, 2021). A disorder of the brain that causes unusual shifts in mood, energy, activity levels and the ability to carry out day-to-day tasks. "Previous studies showed that the FA decrease of ATR was also found in bipolar disorder (BD), indicating that ATR plays an important role in the onset of affective disorders, though this may be related to the different participants." (PMID 34462632, 2021).
bladder squamous cell carcinoma (1 paper, 2025). A squamous cell carcinoma of the bladder arising from metaplastic epithelium. "To reveal compensatory effects of ATR loss due to mutational events or ATRi treatment induced resistance we used ATRi-sensitive patient-derived bladder squamous cell carcinoma cell cultures to mimic ATRi-resistant models." (PMID 41387887, 2025).
brain malformations (1 paper, 2020).
breast invasive carcinoma (1 paper, 2019). "Interestingly, a positive correlation between ATM, ATR, BRCA1, BRCA2, and KMT2C expression is also derived from TCGA data GBM, LGG, AML, DLBL, SARC, and breast invasive carcinoma (BRIC) RNA‐seq data." (PMID 30665945, 2019).
cardiac hypertrophy (1 paper, 2024). "Lastly, to explore if ATR-127 has any potential to adversely affect hearts, we performed a basic assessment of heart weight in DIO mice and did not observe any difference between the treated and untreated groups, implying that ATR-127 does not induce cardiac hypertrophy." (PMID 38796310, 2024).
Caroli disease (1 paper, 2016). Caroli disease (CD) is a rare congenital liver disease characterized by non-obstructive cystic dilatations of the intra-hepatic and rarely extra-hepatic bile ducts. "In this context, we note that ATR-, PCNT- and ORC1-deficient patients display skeletal abnormalities, and there is mounting evidence that cilia function during skeletogenesis, and at least one ATR-SS patient, has been described with multiple liver cysts indicative of Caroli's disease." (PMID 26908596, 2016).
choriocarcinoma (1 paper, 2022). An aggressive malignant tumor arising from trophoblastic cells. "The fact that STING activation also occurs with ATR inhibitors further suggests that ATR inhibitors may be especially useful in resistant choriocarcinoma as well." (PMID 35301407, 2022). "Immune checkpoint blockade has demonstrated clinical activity in choriocarcinoma, so a similar strategy combining ATR inhibitors with immune checkpoint inhibitors may be active in choriocarcinoma." (PMID 35301407, 2022). "Hence, our results suggest that ATR inhibition could be efficient as a monotherapy for the treatment of MTX-resistant choriocarcinoma." (PMID 35301407, 2022).
chronic leukemia (1 paper, 2017). A slowly progressing leukemia characterized by a clonal (malignant) proliferation of maturing and mature myeloid cells or mature lymphocytes. "Currently, no mutations affecting ATR have been annotated in acute and chronic leukemia patients, and only one case of single-nucleotide variant (SNV) out of 50 samples has been described in AML patients." (PMID 28356161, 2017). "Similarly to ATR, no mutations have been reported in CHK1 in acute and chronic leukemias." (PMID 28356161, 2017).
Cirrhosis (1 paper, 2015). A chronic disorder of the liver in which liver tissue becomes scarred and is partially replaced by regenerative nodules and fibrotic tissue resulting in loss of liver function. "Similar to ATR, Chk1 mRNA expression is correlated with that of ERH (correlation coefficient = 0.504, p < 0.001), and Chk1 mRNA expression was higher in HCCs compared to normal tissues, cirrhosis tissue or dysplastic lesions." (PMID 25880358, 2015).
Cushing syndrome (1 paper, 2022). Cushing's syndrome (CS) encompasses a group of hormonal disorders caused by prolonged and high exposure levels to glucocorticoids that can be of either endogenous (adrenal cortex production) or exogenous (iatrogenic) origin. "ATR-101, an ACAT1 inhibitor, is effective in the treatment of Cushing’s syndrome in dogs." (PMID 36361592, 2022).
cystic kidney (1 paper, 2021). "In this regard, we speculated whether inhibition of either ATR or ATM could further increase genomic instability in cystic kidney epithelial cells, leading to cell death." (PMID 33802342, 2021).
dementia (1 paper, 2013). Loss of intellectual abilities interfering with an individual's social and occupational functions. "The expression of CCL-checkpoint and DNA damage response genes: MDM4, ATM and ATR was strongly upregulated and associated with progression of dementia (cognitive dementia rating, CDR), appearing as early as questionable or mild dementia (CDRs 0.5–1)." (PMID 23861893, 2013).
developmental delay (1 paper, 2021). "O'Driscoll M and colleagues suggested a causal relationship between dysfunction in ATR signaling and developmental delay." (PMID 33859276, 2021).
DNA repair disorders (1 paper, 2025). "Finally, exploring other therapies with activity against DNA repair disorders, such as ATR inhibitors, or even immunotherapy combinations with novel targets, could identify personalized treatment options for patients with BAP1 loss." (PMID 40361508, 2025).
esophageal squamous cell carcinoma (1 paper, 2024). Esophageal squamous cell carcinoma (ESCC) is a type of esophageal carcinoma (EC) that can affect any part of the esophagus, but is usually located in the upper or middle third. "In esophageal squamous cell carcinoma (ESCC), elevated expression of lncRNA-NORAD in radioresistant ESCC cells was found to confer RT resistance via EEPD1/ATR/Chk1 signalling and by inhibiting pri-miR-199a1 processing and the exosomal transfer of miR-199a-5p." (PMID 38802766, 2024).
eye cancers (1 paper, 2024). "Additionally, other genes such as ATR, RAD18, and FANCD2 were the most frequently mutated in specific cancer types such as skin, kidney, and eye cancers, respectively." (PMID 39421870, 2024).
familial breast cancer (1 paper, 2023). "There is evidence that germline mutations in ATR are enriched in patients with familial breast cancer and that ATR/CHK1 may serve as therapeutic targets in TNBCs." (PMID 37390209, 2023).
Granuloma (1 paper, 2020). A compact, organized collection of mature mononuclear phagocytes, which may be but is not necessarily accompanied by accessory features such as necrosis. "Indeed, persistent TLR2-mediated activation of ATR has recently been found to promote polypoid macrophage differentiation, a feature of granulomas, indicating that this kinase cascade might play an important role in development of chronic infection." (PMID 31951200, 2020).
HBOC syndrome (1 paper, 2020). "In addition, our work expands the landscape of variants linked to HBOC syndrome in the Brazilian population, and also depicts the first report of the novel ATR missense variant p.Pro932Thr (c.2794C > A)." (PMID 32039725, 2020).
HCMV infection (1 paper, 2022). "RL1 might thus prevent SLFN11-mediated repression of ATM/ATR in the presence of the DNA damage response stimulated by HCMV infection in order to benefit viral replication." (PMID 35105802, 2022).
heart failure (1 paper, 2021). Inability of the heart to pump blood at an adequate rate to meet tissue metabolic requirements. "End-stage heart failure induced by pressure overload for 9 weeks was associated with (i) decreased α4 protein expression, (ii) increased activity of ATM/ATR protein kinases and (iii) increased H2AX expression and Ser139 phosphorylation." (PMID 33737606, 2021). "Furthermore, pressure overload-induced heart failure was associated with reduced α4 protein expression, increased ATM/ATR protein kinase activity, increased H2AX expression and Ser139 phosphorylation." (PMID 33737606, 2021).
Hypertension (1 paper, 2014). The presence of chronic increased pressure in the systemic arterial system. "In this study, we demonstrated similar findings in WKY and in SHR as already reported, indicating that hypertension did not affect the ATR expression patterns with age." (PMID 24533163, 2014).
infectious mononucleosis (1 paper, 2019). A condition characterized by an increase in mononuclear white blood cells and swollen lymph nodes, which is usually caused by infection with the Epstein-Barr virus. "However, we have also shown that to avoid intra-S phase arrest, EBV disables ATR-mediated phosphorylation of Chk1 through the activities of STAT3 and caspase 7 in cultured EBV-infected cells and in proliferating cells in the blood of patients with infectious mononucleosis." (PMID 31841561, 2019).
intestinal tumors (1 paper, 2017). "Our data suggest that Ino80 insufficiency inhibited intestinal tumors in Apcmin/+ mice by increasing the replication stress-induced activation of ATR-Chk1 signaling and thereby increasing apoptosis." (PMID 29383140, 2017).
ischemia (1 paper, 2022). A hypoperfusion of the BLOOD through an organ or tissue caused by a PATHOLOGIC CONSTRICTION or obstruction of its BLOOD VESSELS, or an absence of BLOOD CIRCULATION. "More recently, suppression of necrotic cell death caused by Ca2+ overload associated with ischemia has also been reported as another non-canonical and CHK1-independent function for ATR." (PMID 35754741, 2022).
Kallmann syndrome (1 paper, 2023). Kallmann syndrome (KS) is a developmental genetic disorder characterized by the association of congenital hypogonadotropic hypogonadism (CHH) due to gonadotropin-releasing hormone (GnRH) deficiency, and anosmia or hyposmia (with hypoplasia or aplasia of the olfactory bulbs). "We recently reported that the N-methyl-D-aspartate receptor synaptonuclear signaling and neuronal migration factor (NSMF), a neuronal protein associated with Kallmann syndrome, promotes RPA32 phosphorylation via ATR upon replication stress." (PMID 37378431, 2023).
Kidney Cyst (1 paper, 2021). Abnormal fluid filled sac within the kidney, either acquired or congenital. "The present study aimed to begin to evaluate this hypothesis and specifically investigate whether reducing either ATM or ATR attenuates kidney cyst growth." (PMID 33802342, 2021). "This study hypothesized that reducing either ATM or ATR attenuates kidney cyst formation and growth in experimental ADPKD." (PMID 33802342, 2021). "The functional significance of ATM or ATR in mediating kidney cyst growth in ADPKD is however not known." (PMID 33802342, 2021).
laryngeal tumors (1 paper, 2020). "In contrast to laryngeal tumors in TCGA, our cohort contained recurrent focal copy loss in genes associated with DNA damage repair (ATM, ATR, and BRCA2)." (PMID 33105726, 2020).